CD4 (CD4 molecule)
Diseases named in the same sentence as CD4 in open-access papers (continued):
Sharing a sentence is not in itself a finding about the gene and the disease.
infection (continued). "Moreover, CD8+ memory T cells are responsible for secondary infection control along with CD4+ T cells." (PMID 31849951, 2019). "CD4+ frequencies in CD34+ cells before infection were lower than those in CD34− cells." (PMID 30761146, 2019). "During infection with the Old World species L. major, the resistant and susceptible phenotypes of C57BL/6 and BALB/c murine models are determined by their respective Th1- and Th2-mediated CD4+ T cell responses." (PMID 30756088, 2019). "However, SP-A and SP-D enhanced the infection of immature monocyte-derived DCs (IMDDCs) and transfer to the CD4+ T cell line, upon co-culture." (PMID 30293076, 2019). "These blocks to replication in macrophages may put high-affinity CD4 binders at an evolutionary disadvantage during early stages of infection." (PMID 31181085, 2019). "In particular, no sign of overt infection (plasma viremia, CD4+ T-cell loss) were detected in nine of the 12 animals that were vaccinated with Tat (protein or DNA), even though a few proviral DNA copies were sporadically found in a few animals." (PMID 31454973, 2019). "Replication was then measured following in vitro infection of naïve primary rhesus CD4+ T cells." (PMID 30943274, 2019). "Moreover, in accordance with data about the prevalence of a polyfunctional T-cell profile in natural infection, we observed B. anthracis CD4+ T-cells able to produce both IFNγ and TNFα." (PMID 31213220, 2019). "However, in a study the results showed that there is no a significant difference between two ART and ART-naïve groups regarding to their counts of CD4 and the level of progression of infection." (PMID 31665007, 2019). "Both IL-4 and IL-13 inhibit IFN-γ-producing CD4+ T-cells and suppress protective Th1 immune response and trigger MΦs to undergo alternative activation resulting in parasite survival and persistence of infection." (PMID 31024534, 2019). "It is worth investigating in future studies how this process might tip the balance in favor of DC-mediated viral trans-infection over killing of CD4 T cells." (PMID 31398241, 2019). "Infection of CD4+ T cells resulted in a ~15% drop in their viability." (PMID 31308388, 2019). "We tested 10 participants under suppressive ART and found that B cells and DCs derived from these individuals mediated efficient trans infection of autologous CD4+ T cells compared with trans infection mediated by APCs archived before therapy initiation (respectively)." (PMID 31304185, 2019). "Adoptive transfer of CXCR6-deficient and WT P25-specific CD4+ T-lymphocytes showed an increase of CXCR6-deficient cells in the lungs and BAL at day 7 after PR8-P25 infection, but by day 20 equivalent numbers of WT and CXCR6-deficient cells were present at all sites." (PMID 30899256, 2019). "Moreover, we found that protein vaccination leads to memory CD4 T cells that can be recalled by infection." (PMID 31694141, 2019). "As before, RhIVSF162 infection was cleared and CD4+ T-cells recovered." (PMID 31644426, 2019). "However, they can also regulate effector function of T cells and consequently, loss of INFAR in Tregs results in impairment of CD4+ and CD8+ T cell responses and compromised viral clearance following LCMV-Arm infection." (PMID 30791575, 2019). "Direct infection of cells via the CD4 molecule and co-receptors is termed cis-infection." (PMID 31487324, 2019). "However, genetic diversity of HIV-1 and independent viral evolution in monocytes and CD4+ T cells during the course of infection in treated and untreated patients suggests cellular compartmentalization." (PMID 31866988, 2019). "We hypothesised that if TF Envs were enriched with high mannose compared to CI variants then they would bind DC-SIGN with high affinity resulting in enhanced CD4+ T cell trans-infection." (PMID 31208438, 2019).
infection (continued). "Since incubating DC-SIGN-Fc with 1μg/ml SEA provided a 70% reduction in its capacity to bind gp140, we pre-incubated Raji DC-SIGN cells with the same concentration to identify whether SEA can block HIV-1 trans-infection of CD4+ T-cells." (PMID 31487324, 2019). "Monitoring lymphocyte subsets, especially CD4+T cells, may be helpful for identifying the presence of infection in SLE patients." (PMID 30994732, 2019). "Obvious increase of CD103+ CD4+ T cells could be detected only in week 5 after infection (P < 0.05)." (PMID 31775660, 2019). "Apart from its fundamental role in supporting B cell latency in MHV68 infection, CD4+ T cells may also control MHV68 replication in a CD8+ T cell dependent or independent manner." (PMID 30828337, 2019). "In addition, many studies have observed infected DCs have superior viral transfer capacities than CD4+ T cells and can often efficiently spread infection even in limiting numbers." (PMID 31156637, 2019). "Transgenic OT-II mice did not exhibit corneal sensation loss following infection despite evidence of bystander CD4+ T cell activation and recruitment into the cornea." (PMID 31414985, 2019). "Vaccines that can stimulate both CD4+ and CD8+ T cell responses to HIV-1 may be able to control the virus early in infection before the virus causes major immune damage, as was demonstrated with the partial efficacy obtained in the RV144 trial." (PMID 31817622, 2019). "Other investigators have attempted to determine with limited success whether EC/VC CD4 +T cells are resistant to infection in vitro." (PMID 30964004, 2019). "We cultured Bcl-2-expressing CD4+ T cells for 10 weeks to maintain quiescent infection." (PMID 30976083, 2019). "We then evaluated the impact of the pharmacological inhibition of CBP/β-catenin interaction on the persistent viral reservoir by measuring by PCR the frequency of infection of CD4+ T cell subsets sorted by fluorescence-activated cell sorting (FACS) from the peripheral blood." (PMID 31619550, 2019). "Poor treatment adherence might allow viral replication which in turn increases infection of more CD4+ T cells and ultimately depletion of their number." (PMID 31805857, 2019). "However, over time, they regained control of infection, as indicated by the statistically significant and long-lasting reduction of viral replication and CD4+ T-cell number restoration in comparison to the control monkeys." (PMID 31454973, 2019). "HIV might also modify the turnover of HSPCs through infection and depletion of CD4+ cells, leading to the common manifestation of bone marrow abnormalities." (PMID 30761146, 2019). "In addition, the natural CHIKV viral epitopes identified in the current report open a new way of studying more specifically the role of both CD4+ and CD8+ T lymphocytes in the infection as well as in the chronic pathology caused by CHIKV." (PMID 31276466, 2019). "We next tested whether SEA could interfere with HIV-1 cis-infection of CD4+ lymphocytes (direct infection)." (PMID 31487324, 2019). "To confirm that the viruses measured in MΦ-QVOAs were replication competent and capable of producing de novo infection, we infected activated CD4 T cells isolated from a healthy rhesus macaque with supernatant collected from MΦ-QVOA wells and assessed viral kinetics." (PMID 31431552, 2019). "CECs are more efficient than RBCs at mediating HIV-1 trans-infection of CD4+ T cells." (PMID 31772057, 2019). "However, at 7 days post-infection, the number of CD4+ and CD8+ T cells was reduced in the lungs of infected mice." (PMID 30936869, 2019). "In addition, in order to show the unequivocal upregulation of CD20 after HIV infection, we performed cell sorting of the CD4+ CD20− population before cell infection." (PMID 31420544, 2019).
infection (continued). "It is also of interest that recent human trials examining BCG revaccination or M. tuberculosis protein subunit vaccines H4/IC31 or M72/AS01E, all of which predominantly stimulate CD4+ T- lymphocyte responses, demonstrated a significant level of protection against sustained infection." (PMID 30899256, 2019). "Although majority, 91 (47.2%) had CD4+ T values greater than 500 cells/mm3, there was no significant statistical association between CD4+T counts and hrHPV infection." (PMID 31558924, 2019). "Therfore at this level of CD4 count, we can realize the infection as a disease." (PMID 31665007, 2019). "We propose that Siglec-1+ cervical DCs may facilitate HIV-1 transfer to bystander CD4+ T cells and favor the nascent infection within the cervical mucosa, but also facilitate early dissemination to secondary lymphoid tissues." (PMID 31114569, 2019). "Interestingly, kinetic changes of the CD4+ and CD8bright T cell populations over the course of acute disease were opposite from animals that succumbed to infection." (PMID 31166946, 2019). "After infection, CD4+ T cells displayed an increased capacity in producing IFN-γ also." (PMID 31930147, 2019). "The changes seen above could impact the ability of WT versus Il2-/- memory CD4 T cells to protect against infection." (PMID 31412088, 2019). "Two Envs were cloned at 5 and 173 wpi and selected for mutational analysis as they both carried N241, N262, N386, N392 and N448, unlike other clones, and these were compared for Env expression and mannosylation as well as PSV entry efficiency, DC-SIGN binding and trans-infection of CD4+ cells." (PMID 31208438, 2019). "After infection of target cells with recMVA or MHV-68 encoding ORF61 a ribonuleotide-reductase large subunit protein, CD8+ T cells were specifically activated, while CD4 T cells were less responsive (recMVA) or completely failed to respond (MHV-68)." (PMID 31921215, 2019). "Consistent with our previous findings, the frequency of IL-4+ CD4+ T cells was significantly increased at all time points in the spleen (part A) and mesenteric nodes (part B), with the frequency increasing as the infection progressed." (PMID 30653492, 2019). "Both independently and by interaction, protein malnutrition and infection induced a significant decrease in the percentage of double positive T cells (CD4+CD8+ T cells, DP) proliferating and that had recently proliferated, based on Ki67 expression, in the thymus of BALB/c mice (p < 0.001)." (PMID 31355153, 2019). "However, gp120/CD4 conjugates can transiently occur during viral entry, when the virion binds to CD4+ cells during infection, but also on the surface of uninfected CD4+ bystander cells." (PMID 31141927, 2019). "Similarly, previous evidence from our laboratory has shown that VitD can reduce the infection of CD4+ T cells in vitro." (PMID 31611877, 2019). "Interestingly, the rate of change in CD4+ and CD8bright T cell populations in the survivor over the course of the acute disease, were the reverse of animals that succumbed to infection." (PMID 31166946, 2019). "Consistent with a role for SmCB1 activity in driving TH2 responses in mice, K11777 treatment reduced the frequency of eGFP+ CD4+ T cells in the spleens of infected mice at 4 weeks post infection, and reduced the titers of worm-specific IgE in the plasma of infected mice." (PMID 30653492, 2019). "The loss of CD4+ T cells persists through the chronic stage of infection, in which most of the cell death seems to be driven by bystander killing of CD4+ T cells that were not actively infected." (PMID 31191468, 2019). "The innate immune receptor DC-SIGN (dendritic cell-specific intercellular adhesion molecule-3 grabbing non-integrin) is a well-known enhancer of HIV infection that binds to the HIV envelope glycoprotein gp120 and promotes efficient infection in trans of cells that express CD4 and CCR5." (PMID 30871222, 2019).
infection (continued). "Besides being metabolically inactive, several other factors impede infection of naïve or memory CD4+ T-cells by HIV-1." (PMID 31487807, 2019). "This might be true for Swaziland as well, given that, as more than 90% of the study participants were on ART, most of them had CD4 counts of 200 cells/microliter or even lower at TB diagnosis, which may be the reason for infection." (PMID 31429717, 2019). "To investigate whether MAH 11 is suitable for studying MAH-specific host immune responses, we measured mycobacterium-specific CD4+ T cell responses after mouse infection." (PMID 31822597, 2019). "While our studies are hopeful in that the majority of AE are immunogenic in chronic infection, they also indicate that these CD8 T cells may be continuing to drive the infection of CD4 T cells." (PMID 31398241, 2019). "Indeed, at day 30 post-infection CD4+ T cell as well as pan T cell-specific IL-4Rα−/lox mice (iLckcreIL-4Rα−/lox) were more." (PMID 31475014, 2019). "We next evaluated whether mac-tropic R5 Envs from brain tissue of neuroAIDS patients had evolved an enhanced binding affinity for CCR5 that might facilitate CD4-independent infection via CCR5." (PMID 30415390, 2019). "Accordingly, we collected CD4+ T cells from peripheral blood in this study at 21-days post-infection (late cytolytic phase) for RNA sequencing to investigate whether MDV infection results in transcriptomic level changes of CD4+ T-lymphocytes." (PMID 31798630, 2019). "Of note, the frequencies of small intestinal CD4+ effector cells expressing RORγt+ and IL-17A+ remained stable upon infection in both mouse lines despite significantly higher proportions of siLP Th17 cells expressing the proliferation marker Ki-67 in infected C57BL/6 mice." (PMID 31889073, 2019). "An analysis of the immune responses revealed a trend to reduced induction of Env-specific CD4+ T cells and a severely impaired induction of neutralizing antibodies upon FV challenge infection in MCMV pre-immune mice compared to pre-naïve MCMV.env immunized mice." (PMID 31568492, 2019). "In the context of infections, B cells are known not only to produce antibodies involved in pathogen clearance, but also to enhance ongoing immune response by performing highly specialized antigen presentation to CD4+ T cells." (PMID 31824487, 2019). "In addition to innate cells, the clearance of bacteria from the tissues also requires functional CD4 T cells, resulting in long-lasting specific immunity to re-challenge infection." (PMID 32038650, 2019). "It is feasible that abortive infection of CD4+ T cells, which has previously been observed during HIV-infection, may partially occur through the phosphatidylserine (PtdSer)-Tim-1 interactions." (PMID 31648236, 2019). "There are many subsets of CD4+ T cells, such as T-helper 1 (Th1), Th2, Th17, follicular helper (Tfh), and regulatory T cells (Tregs), and all these subsets cooperate or interfere with each other to control infection." (PMID 31111075, 2019). "Indeed, transfer of monocytes to the NFAT1−/− mice partially control of parasites and restored the CD4+ T lymphocyte recruitment to the CNS and longer survival up to 40 days post-infection." (PMID 31555297, 2019). "HIV-1 infects cells through binding of HIV gp120env with the CD4 membrane glycoprotein, and therefore all cell types expressing this marker could potentially accommodate infection." (PMID 31129856, 2019). "Furthermore, CD4+ T cell depletion was found to be more profound upon infection with ICAM-positive virions." (PMID 30669528, 2019). "Indeed, rapid decline of CD4 counts and disease progression has also been reported when infection is initiated by dual CCR5/CXCR4 dual-tropic or CXCR4-tropic HIV strains." (PMID 30761146, 2019).
infection (continued). "Further investigation of the role of CD4+ T cells demonstrated that during the acute phase of infection, there was a significant upregulation of an IFN-γ-specific CD4+ T cell (Th1) response followed by an IL-4-specific CD4+ T cell-mediated (Th2) antibody response during the chronic phase." (PMID 30774635, 2019). "Importantly, KCC1M935K/M935K showed an 8-fold increase in CD4+ T cells in the brain during infection (P = 0.028) compared to the CD4+ T cells in infected WT, but only a 2-fold increase from their already higher baseline." (PMID 31015511, 2019). "By moderating neutrophil infiltration, the absence of eNOS may reduce the collateral damage to kidney cortex, and Th-9 CD4+ cells may enhance clearance of the infection." (PMID 31671151, 2019). "In addition, when CD4 T cells are depleted in macaques prior to infection with SIVmac251, the infection results in high viral load, infection of myeloid cells in the brain, and the development of encephalitis." (PMID 31431552, 2019). "Furthermore, the responding CD4+ T cells had different functional profiles at the two stages of infection." (PMID 31308093, 2019). "Thus, APCs from participants on virus-suppressive ART and tested ex vivo can efficiently mediate HIV-1 trans infection of CD4+ T cells that are resistant to direct cis infection." (PMID 31304185, 2019). "Additionally, and as observed 2 weeks after infection, differences in CD4+CXCR5+PD1+ T cells were detected, comparing the different mouse strains, regarding both basal levels and the ones determined in 8-week-infected animals." (PMID 30881923, 2019). "Importantly, this was confirmed and extended by demonstrating that ex vivo DCs and B cells from ART-suppressed PWH were able to mediate highly efficient trans infection of CD4+ T cells that were relatively resistant to direct cis infection." (PMID 31304185, 2019). "Poor CD4 cell recovery has been associated with age and telomere length, male sex, hepatitis C co-infection, pre-treatment CD4 counts, pre-treatment HIV RNA viral load (VL), specifics of the cART regimen, and duration of infection prior to cART initiation." (PMID 31415590, 2019). "Similar to the re-infection experiment, we found that mice receiving CD4 T cells from celecoxib-treated animals had a higher lung bacterial burden at week 6 of the infection, indicating that the long-term protective capacity of the CD4 T cells was compromised by the celecoxib treatment." (PMID 31396568, 2019). "The induction of sustained and broadly directed HCV-specific CD4+ and CD8+ T cell responses, together with neutralizing antibodies (nAb), and specific genetic polymorphism have been associated with spontaneous resolution of the infection." (PMID 30987134, 2019). "Adopting the principles used in host-parasite interactions for the processes of attachment and entry of the virus into CD4+ T cells, we assume that the infection of CD4+ T cells is determined by the number of contacts/encounters of the virus with the CD4+ T cells." (PMID 31532803, 2019). "The results have been confirmed using tetramers specific for two different antigens, thus strengthening the possible application of the selected procedure to the characterization of the complex functional profile of CD4+ T-cell responses upon vaccination or infection." (PMID 31649661, 2019). "In a mouse model, the Env-CaP-p30 nanoparticle-based vaccine was able to improve HIV-1 Env-specific antibody responses without additional induction of HIV-specific CD4 T-cells suspected to increase the susceptibility to infection." (PMID 31569763, 2019). "FeTJ cells are IL2 independent, CD4+, immortalized cells that are susceptible to FIV infection." (PMID 31600877, 2019). "We also determined if potential ex vivo carryover of antiviral drug activity could affect direct cis infection of CD4+ T cells, comparing PBMCs obtained from the same MACS participants before and after initiation of ART." (PMID 31304185, 2019).